CRYBA4 (crystallin beta A4)
Description:
Crystallins are the dominant structural components of the vertebrate eye lens.
Synonyms: CTRCT23; CYRBA4; MCOPCT4
Tractability: No criterion of Open Targets' tractability assessment is met for any kind of drug.
Gene: Protein-coding gene on chromosome 22 (26,621,963 to 26,630,669, forward strand). Ensembl gene ENSG00000196431.
Pathways (Reactome):
Cellular responses to stimuli: Attenuation phase; HSF1 activation; HSF1-dependent transactivation; Regulation of HSF1-mediated heat shock response
Gene Ontology:
Molecular function: identical protein binding; protein binding; structural constituent of eye lens
Biological process: camera-type eye development; visual perception; lens development in camera-type eye
Genetic constraint (gnomAD): Loss-of-function variants: 30 observed, 32.88 expected, observed/expected ratio (o/e) 0.91, 90% interval 0.68 to 1.24. The upper end of that interval is the gene's LOEUF score, 1.24, which puts it in group 5 of 6, group 1 being the genes least tolerant of losing a copy. Missense variants: 225 observed, 273.27 expected, observed/expected ratio (o/e) 0.82, 90% interval 0.74 to 0.92. Synonymous variants: 102 observed, 107.8 expected, observed/expected ratio (o/e) 0.95, 90% interval 0.81 to 1.12.
Homologues: Orthologues: chimpanzee CRYBA4 (99% identical), macaque CRYBA4 (97% identical), rabbit CRYBA4 (94% identical), guinea pig CRYBA4 (93% identical), mouse Cryba4 (92% identical), rat Cryba4 (92% identical), pig CRYBA4 (91% identical), dog CRYBA4 (81% identical), tropical clawed frog cryba4 (75% identical), zebrafish cryba4 (68% identical). Paralogues in human: CRYBA1 (66% identical), CRYBA2 (53% identical), CRYBB1 (43% identical), CRYBB3 (40% identical), CRYBB2 (39% identical), CRYBG2 (35% identical), CRYGC (33% identical), CRYBG3 (32% identical), CRYBG1 (32% identical), CRYGB (31% identical), CRYGA (30% identical), CRYGS (30% identical), and 2 more.
Diseases named in the same sentence as CRYBA4 in open-access papers:
CRYBA4 is named in the same sentence as 9 diseases in open-access papers, as found by Europe PMC text mining. Sharing a sentence is not in itself a finding about the gene and the disease. The quoted sentences say what the papers report.
microphthalmia (6 papers, 2009 to 2025). Congenital or developmental anomaly in which the eyeballs are abnormally small. "It is a known fact that complex microphthalmia in association with genetic cataracts has been attributed to mutations in the CRYBA4 gene." (PMID 32962661, 2020). "First, previous studies have identified mutations in the CRYBA4 gene responsible for cataract, microcornea and microphthalmia." (PMID 22792142, 2012). "However, mutations in VSX2, CRYBA4, OTX2, and RAX have been detected in about 2%–3% patients with microphthalmia, anophthalmia, and coloboma." (PMID 20057906, 2009). "Mice/humans with variants in other cataract-associated genes, such as crystallins can also manifest with complex features including corneal anomalies, iris hypoplasia and microphthalmia [(CRYAA; CRYBB1; CRYBA4]." (PMID 40301690, 2025). "Mutations in several genes have been reported in patients with microphthalmia and/or coloboma, including BMP4 (OMIM 112262), VSX2 (CHX10; OMIM 142993), CRYBA4 (OMIM 123631), OTX2 (OMIM 600037), RAX (OMIM 601881), SIX6 (OMIM 606326), and SOX2 (OMIM 184429)." (PMID 20057906, 2009).
congenital cataracts (2 papers, 2017 to 2022). "They suggested that CRYBA4 p.A9V may be the pathogenic mutation of a Chinese family with congenital cataracts." (PMID 28450710, 2017). "A subset of the 7-days radiation only DEG (Cryaa, Cryba1, Cryba2, Cryba4, Crybb1, Crybb2, Crybb3, Crygs, Bsfp1) were enriched in nuclear and congenital cataracts, however, these genes were not dysregulated at 1 month or 4 months." (PMID 36207342, 2022).
Microcornea (2 papers, 2010 to 2012). A congenital abnormality of the cornea in which the cornea and the anterior segment of the eye are smaller than normal. "It expands the mutation spectrum of CRYBA4 and provides useful information to the study of molecular pathogenesis of cataract and microcornea." (PMID 20577656, 2010). "We report a novel missense mutation in CRYBA4 after analyzing a Chinese family with congenital cataract and microcornea." (PMID 20577656, 2010).
myopia (1 paper, 2012). "Based on the analysis results, we found crystallin beta A4 (CRYBA4) to be a novel gene for myopia susceptibility." (PMID 22792142, 2012). "The present case-control study identified a novel susceptibility gene (CRYBA4) for high myopia in southern Chinese." (PMID 22792142, 2012). "In other words, the positive association between CRYBA4 and high myopia is robust to these potential confounding factors." (PMID 22792142, 2012). "Indeed, by the initial and the replication case-control association studies, we found significant association of CRYBA4 with high myopia." (PMID 22792142, 2012). "These ocular disorders may partly share their underlying pathology, which supports the present finding of association between CRYBA4 and high myopia." (PMID 22792142, 2012). "CRYBA4 and many other crystallin genes show strong and sustained up-regulation after retinal injury, and expression changes in both protein and mRNA levels in the sclera of guinea pig during form deprivation myopia and subsequent recovery." (PMID 22792142, 2012).
Retinal coloboma (1 paper, 2012). A notch or cleft of the retina or choroid, located vertically below the optic disc. "Moreover, another mouse study suggested that tissue-specific over-expression of Rybp (a zinc finger protein) in the lens could reduce CRYBA4 gene expression while heterozygous Rybp null mice often resulted in retinal coloboma characterized by expanding localization of PAX6." (PMID 22792142, 2012).
CRYBA4 also shares sentences with these, for which no sentence is quoted: cataract (3 papers); breast carcinoma (1); coloboma (1); Nystagmus (1).